SIGLEC12 (sialic acid binding Ig like lectin 12)
Description:
Putative adhesion molecule that mediates sialic-acid dependent binding to cells. The sialic acid recognition site may be masked by cis interactions with sialic acids on the same cell surface.
Synonyms: Siglec-12; Siglec-L1; SIGLECL1; SLG; S2V; Siglec-XII
Tractability: Antibody: UniProt predicts a signal peptide or a membrane-spanning region; its Gene Ontology location is reachable by antibodies, with medium confidence.
Gene: Protein-coding gene on chromosome 19 (51,491,227 to 51,501,800, reverse strand). Ensembl gene ENSG00000254521.
Subcellular location: Membrane
Pathways (Reactome):
Immune System: Immunoregulatory interactions between a Lymphoid and a non-Lymphoid cell
Gene Ontology:
Molecular function: protein binding; sialic acid binding
Biological process: cell adhesion
Cellular component: plasma membrane; membrane
Genetic constraint (gnomAD): Loss-of-function variants: 40 observed, 53.96 expected, observed/expected ratio (o/e) 0.74, 90% interval 0.57 to 0.96. The upper end of that interval is the gene's LOEUF score, 0.96, which puts it in group 4 of 6, group 1 being the genes least tolerant of losing a copy. Missense variants: 795 observed, 752.12 expected, observed/expected ratio (o/e) 1.06, 90% interval 1 to 1.12. Synonymous variants: 353 observed, 317.22 expected, observed/expected ratio (o/e) 1.11, 90% interval 1.02 to 1.22.
Homologues: Orthologues: chimpanzee SIGLEC8 (97% identical), mouse Siglece (40% identical), rat Siglec8 (40% identical), tropical clawed frog siglecl2 (20% identical), tropical clawed frog siglecl2 (18% identical), tropical clawed frog siglecl1 (18% identical), tropical clawed frog siglecl1 (13% identical). Paralogues in human: SIGLEC7 (59% identical), SIGLEC8 (57% identical), SIGLEC9 (55% identical), SIGLEC6 (38% identical), SIGLEC5 (36% identical), SIGLEC10 (33% identical), SIGLEC11 (32% identical), SIGLEC14 (31% identical), CD33 (30% identical), SIGLEC1 (19% identical), MAG (16% identical), SIGLEC16 (15% identical), and 4 more.
Diseases named in the same sentence as SIGLEC12 in open-access papers:
SIGLEC12 is named in the same sentence as 25 diseases in open-access papers, as found by Europe PMC text mining. Sharing a sentence is not in itself a finding about the gene and the disease. The quoted sentences say what the papers report.
colorectal cancer (4 papers, 2021 to 2025). A primary or metastatic malignant neoplasm that affects the colon or rectum. "This is in agreement with a previous study in colorectal cancer, where SIGLEC12 has a functional allele." (PMID 41303731, 2025). "Our research on SIGLEC12’s impact on colorectal cancer, using an integrated evolutionary genetics-phenome-transcriptome approach, surprisingly revealed a novel genetic mechanism for ethnic environmental carcinogenesis." (PMID 38990656, 2024). "Similarly, SIGLEC12 expression is related to the pro-oncogenic and inflammation phenotypes in colorectal cancer." (PMID 41303731, 2025). "High frequency of SIGLEC12 expression in advanced colorectal cancer cohort and correlation with OS." (PMID 35962453, 2022). "Although several risk factors in BCa have been documented, and high SIGLEC12 expression levels are shown in colorectal cancer and renal cancer, the role of SIGLEC12 in BCa has not been documented." (PMID 41303731, 2025).
prostate carcinoma (3 papers, 2021 to 2025). A carcinoma that arises from epithelial cells of the prostate gland. "Previous studies showed that while the non‐Sia‐binding Siglec‐XII can be expressed in SIGLEC12 mutated PC‐3 human prostate cancer cells, efforts to transfect the chimpanzee version of SIGLEC12 or the arginine‐restored version of human SIGLEC12 were not successful." (PMID 33615152, 2021). "Although the SIGLEC12 allele status did not predict prostate carcinoma incidence, forced expression of human Siglec-XII in a null prostate carcinoma cell line increases tumor growth in nude mice." (PMID 41303731, 2025). "To explore molecular mechanisms of Siglec‐XII in cancer progression, we compared RNA expression patterns between SIGLEC12 null PC‐3 prostate cancer cells with and without transfection with a construct encoding Siglec‐XII." (PMID 33615152, 2021).
renal carcinoma (2 papers, 2024 to 2025). A carcinoma arising from the epithelium of the renal parenchyma or the renal pelvis. "In addition, SIGLEC12 is highly expressed in renal cancer and is linked to primary tumor growth, increased immune cell infiltration in the tumor microenvironment, and poor survival in kidney renal clear cell carcinoma and kidney renal papillary cell carcinoma." (PMID 41303731, 2025). "The role of SIGLEC12 in BCa remains unexplored, despite potential involvement in tumorigenesis in prostate, colorectal, and renal cancers." (PMID 41303731, 2025).
bladder (1 paper, 2025). "In this study, we identified epigenetic hypomethylation as a regulatory mechanism for SIGLEC12 overexpression, and methylation deregulation of SIGLEC12 may serve as a universal event in bladder tumorigenesis and progression." (PMID 41303731, 2025).
bladder urothelial carcinoma (1 paper, 2024). "SIGLEC12 expression was found to be upregulated in bladder urothelial carcinoma (BLCA), cervical squamous cell carcinoma (CESC), esophageal earcinoma (ESCA), and Glioblastoma multiforme tumours (GBM) when compared to the normal sample type." (PMID 38268823, 2024).
colon adenocarcinoma (1 paper, 2024). "In contrast, colon adenocarcinoma (COAD), lung adenocarcinoma (LUAD), lung squamous cell adenocarcinoma (LUSC), and pancreatic adenocarcinoma (PAAD) exhibited downregulation of SIGLEC12 when compared to healthy samples." (PMID 38268823, 2024).
oropharyngeal cancer (1 paper, 2023). Carcinoma, predominantly squamous cell, arising from the epithelial cells of the oropharynx. "Most of the oral and oropharyngeal cancer samples were unmethylated in almost all the investigated gene promoters: EDARADD, GBP4, HAVCR2, HLA DPB1, IL12RB1, MARCO, and SIGLEC12." (PMID 37175405, 2023).
Stillbirth (1 paper, 2012). Death of the fetus in utero after at least 22 weeks of gestation. "The SIGLEC12 gene had large AIPL effects for six functional traits, productive life, daughter pregnancy rate, service-sire calving ease, service-sire stillbirth, daughter calving ease, and net merit." (PMID 23039970, 2012).
cancer (8 papers, 2021 to 2026). A tumor composed of atypical neoplastic, often pleomorphic cells that invade other tissues. "According to The Cancer Genome Atlas (TCGA), 444 missense and 63 truncating mutations have been reported in the exons of SIGLEC12 in 67,030 individuals with cancer (somatic mutation frequency of 0.7%)." (PMID 41225007, 2026). "A SIGLEC12 variant associated with cancer (Ser458Phe) and a variant found in the general human population (Arg528Trp) attenuate SIGLEC12 cleavage by TMPRSS4." (PMID 41225007, 2026). "Here, an integrated evolutionary genetics-phenome-transcriptome approach studied the role of SIGLEC12 gene (encoding Siglec-XII) in epithelial transformation and cancer." (PMID 38990656, 2024). "Individuals who have an ancestral SIGLEC12 allele with an intact open reading frame appear more prone to develop advanced carcinomas." (PMID 33842853, 2021). "Notably, similar to the cancer-associated Ser458Phe variant, the Arg528Trp mutation blocked SIGLEC12 cleavage by TMPRSS4." (PMID 41225007, 2026). "Whether cancer-associated mutations in SIGLEC12 or its variants found in the general population play an important part in the pathogenesis of human diseases, such as sensitivity to infections, in which necroptosis has been implicated, remains to be determined." (PMID 41225007, 2026). "Thus, advanced carcinomas are much more likely to occur in individuals whose genomes have an intact SIGLEC12 gene, likely because the encoded Siglec‐XII protein recruits Shp2‐related oncogenic pathways." (PMID 33615152, 2021). "Although, some studies have researched the role of SIGLEC12 in cancer development, to the best of our knowledge this is the first study assessing the clinical utility and role of SIGLEC12 in RC using multiomics datasets." (PMID 38268823, 2024). "Previous reports have suggested that the SIGLEC12 gene, which encodes the Siglec-XII protein, is expressed in the epithelial tissues and upregulated in carcinomas." (PMID 38268823, 2024). "We appreciate the strongly supportive and positive comments by Voskarides7 about our article published in this journal, which suggested that human‐specific polymorphic pseudogenization of SIGLEC12 protects against advanced cancer progression." (PMID 33842853, 2021). "SIGLEC12 is expressed in the gastrointestinal tract, epithelial cells and macrophages, as well as certain cancers, in which it may contribute to tumour progression." (PMID 41225007, 2026). "Our findings align with reports that SIGLEC12 expression in other cancers predicts worse outcomes." (PMID 41303731, 2025). "Furthermore, we analysed the effect of SIGLEC12 expression on the cancer stage, and the results showed an increase in tumour progression for all stages except for KIRP individuals (p = 0.8)." (PMID 38268823, 2024). "Here, we focus on Siglec‐XII expression in tumor and normal epithelia, identify genes upregulated upon Siglec‐XII expression, address the predictive value of SIGLEC12 status in cancer cohorts, and provide further evidence suggesting ongoing selection for the null state." (PMID 33615152, 2021). "Upregulation of these well‐known oncogenic pathways in individuals with an intact SIGLEC12 allele may explain the molecular mechanisms underpinning our discovery of increased frequency of Siglec‐XII protein in advanced carcinomas." (PMID 33615152, 2021). "Similarly, the expression of SIGLEC12 across the TCGA cancers reinforces the proposition that some cancer may have the SIGLEC12 gene as part of other gene responsible for their tumour formation." (PMID 38268823, 2024). "Taken together, the data above suggest that the genomic status of SIGLEC12 may not be correlated with the early cancer risk, but rather with late progression." (PMID 33615152, 2021). "Given the lack of significant correlation between SIGLEC12 status and carcinoma risk or early stage carcinomas, we reasoned that there might instead be a correlation with late‐stage cancers." (PMID 33615152, 2021).
cancer (continued). "Moreover, our studies represent the first implications of SIGLEC12 in human cancer, with currently unknown potential impact on cancer biology, prevention, and therapy." (PMID 33842853, 2021). "There was no clear correlation of SIGLEC12 status with the progression of these early stage carcinomas." (PMID 33615152, 2021).
tumor (5 papers, 2021 to 2025). "These associations position SIGLEC12 within networks of signaling cascades that sustain tumor growth." (PMID 41303731, 2025). "In this aspect, our results suggest that SIGLEC12 expression is linked to a complex immune contexture, with enrichment in both pro-tumor and anti-tumor immune populations." (PMID 41303731, 2025). "These associations suggest that SIGLEC12 may contribute to an immunosuppressive tumor microenvironment." (PMID 41303731, 2025). "In this study, we demonstrate that SIGLEC12 expression is highly increased at the early stage of BCa due to promoter hypomethylation and is associated with the immune context and oncogenic pathways in the tumor microenvironment, as well as drug resistance." (PMID 41303731, 2025). "SIGLEC12 levels were correlated positively with pro-tumor immune subsets, Tregs (Rho = 0.151, p = 3.61 × 10−3), M0 macrophages (Rho = 0.170, p = 1.07 × 10−3), and M2 macrophages (Rho = 0.454, p = 4.20 × 10−20)." (PMID 41303731, 2025). "This indicates that promoter hypomethylation of SIGLEC12 is progressively reinforced during tumor progression." (PMID 41303731, 2025). "We propose that the interaction of SIGLEC12 with these factors results to a primary outcome of rate alteration and dysregulation leading to the proliferation of neoplasms." (PMID 38268823, 2024). "Both results showed a statistically significant increase in the expression of SIGLEC12 in primary tumour." (PMID 38268823, 2024). "We further elucidated the significance of SIGLEC12 expression in tumour nodal metastasis, result showed a statistically significant increase in the metastases according to the tumour, node, metastasis (TNM) staging framework, N0 in KIRC and N0, N1, N2 in KIRP." (PMID 38268823, 2024). "To understand gender related SIGLEC12 expression in tumour development, we compared normal sample type with males, the normal sample type with females and both genders." (PMID 38268823, 2024). "Furthermore, correlations with HGF suggest that SIGLEC12 is involved in angiogenesis and tumor progression, as HGF promotes motility and invasion." (PMID 41303731, 2025). "Moreover, we assessed the relationship between SIGLEC12 expression and keratin family members in BCa; some of which were shown to correlate with tumor progression." (PMID 41303731, 2025). "SIGLEC12-knockin mice display greater tumor burden in response to chemical carcinogenesis." (PMID 38990656, 2024). "To reemphasize, it is still unclear from this result, whether the high expression of SIGLEC12 seen in secondary lymphoid organs and other tissues may result in the possibility of high SIGLEC12 related tumour prevalence in these tissues." (PMID 38268823, 2024). "•SIGLEC12 upregulated tumours have high expression of oncogenic pathways." (PMID 38268823, 2024). "Interestingly, our analysis suggests that SIGLEC12 expression is intricately linked to a diverse range of immune inhibitory pathways, and elevated SIGLEC12 levels may contribute to an immunosuppressive tumor microenvironment in BCa." (PMID 41303731, 2025). "Furthermore, our findings indicate that SIGLEC12 expression parallels some keratin markers, suggesting that it may serve as an additional indicator of tumor phenotype and prognosis in BCa." (PMID 41303731, 2025). "SIGLEC12 may play a role in tumour progression and the development of cold tumours." (PMID 38268823, 2024). "However, SIGLEC12 expression did not significantly alter overall survival or disease-free survival in the BCa cohort; one reason is due to limited sample sizes, treatment variability, and tumor subtype differences." (PMID 41303731, 2025).
SIGLEC12 also shares sentences with these, for which no sentence is quoted: breast carcinoma (2 papers); cervical squamous cell carcinoma (1); cutaneous melanoma (1); glioblastoma (1); graft versus host disease (1); infection (1); inflammatory bowel disease (1); lung adenocarcinoma (1); lung carcinoma (1); oropharyngeal squamous cell carcinoma (1); ovarian carcinoma (1); pancreatic adenocarcinoma (1); polyp (1); rheumatoid arthritis (1); systemic lupus erythematosus (1).